ALB (albumin)
Diseases named in the same sentence as ALB in open-access papers (continued):
Sharing a sentence is not in itself a finding about the gene and the disease.
Hypoalbuminemia (continued). "The observed hypoalbuminemia could be a result of the influence of many factors and inflammation in both groups, since albumin acts as a negative acute-phase reactant and impacts the nutrition status in some particular studied patients." (PMID 35204237, 2022). "A reduced AG may indicate a decrease in the albumin concentration (hypoalbuminemia) as albumin is the primary non-measured anion." (PMID 35957860, 2022). "Moreover, the 1 yr mortality rate was 48.9% in the non-HAD patients with hypoalbuminemia, as compared with 15.3% in the control group with normal serum albumin (p < 0.001)." (PMID 35268297, 2022). "Indeed, hypoalbuminemia has been reported as a prognostic factor for immune-checkpoint therapy (ICT) in lung cancer, and the Gustave Roussy Immune Score, which is used as a prognostic indicator for ICT, includes low albumin as one of its components." (PMID 35410196, 2022). "In light of present observations, it is to be noted that differences in albumin levels between the cohorts (FARI < 9.67: median albumin 42.9 g/L; FARI ≥ 9.67: median albumin 40.3 g/L) are not to be considered clinically relevant and are beyond established cut-offs of hypoalbuminemia." (PMID 36579608, 2022). "In one study that enrolled 75 patients in the hypoalbuminemia group and 32 patients in the normal group pre-operatively measured levels of serum albumin could not serve as predictors for post-operative complications." (PMID 36105581, 2022). "Albumin is a negative acute phase protein and hypoalbuminemia may have been a marker of severity and duration of inflammation in these cats." (PMID 35450137, 2022). "In subsequent subgroup analyses, HSA infusion still did not affect the patients’ prognosis with significant hypoalbuminemia (<2.5 g/dl) while even tended to have an adverse effect on the group of patients with near-normal (3.0–3.5 g/dl) initial serum albumin levels." (PMID 35721190, 2022). "Moreover, no patients developed hypoalbuminemia or required additional albumin supplementation, suggesting that the serum albumin decline with MCO treatment is tolerable." (PMID 35323729, 2022). "Hypoalbuminemia is a feature of inflammation as confirmed in our study by the inverse relation between albumin and CRP or IL-6, but it might also the consequence of a high clearance of oxidized form of albumin." (PMID 34299080, 2021). "Therefore, large amounts of albumin leakage, which would lead to hypoalbuminemia, did not occur in the present study." (PMID 34112908, 2021). "This might have occurred because previous studies did not consider the relationship of FT3 with albumin as confounding factor, and when hypoalbuminemia was present, conversion of T4 to T3 was decreased, resulting the low FT3 levels." (PMID 33494724, 2021). "In contrast, patients without albumin administration developed hypoalbuminemia." (PMID 34684550, 2021). "Instead, the hallmark hypoalbuminemia observed in children with SAM may be the result of the increased frequency and severity of infection, as albumin is a negative acute phase protein." (PMID 34134040, 2021). "The present investigation aimed at assessing the impact of serum albumin levels on long-term outcomes in a cohort of aspirin-treated T2DM subjects without overt cardiovascular disease, showing hypoalbuminemia to be associated with an enhanced risk of cardiovascular events." (PMID 34239442, 2021). "Even if our findings cannot be extrapolated to subjects without T2DM, analysis of serum levels of albumin may be proposed as novel tool to assess the antiplatelet activity of aspirin in patients with putative hypoalbuminemia." (PMID 34239442, 2021). "A retrospective study of 306 older patients (≥65 years) with serum albumin levels <3.5 g/dL suffering femoral neck fracture and undergoing hip replacement examined the effects of HAS infusion alone or in combination with nutritional supplements to correct hypoalbuminemia (to ≥3.5 g/dL)." (PMID 33925831, 2021).
Hypoalbuminemia (continued). "When compared with single indicator—hypoalbuminemia or hyperphosphatasia, AAPR might contribute to identifying more patients with poor prognosis, because some cases might present with normal serum albumin levels but hyperphosphatasia, or normal serum ALP levels but hypoalbuminemia." (PMID 33685425, 2021). "In the vast majority of cases pre-fracture albumin tests were not available so it is difficult to conclude whether hypoalbuminemia reflects a low premorbid nutritional level or whether it is associated with perioperative stress." (PMID 33163503, 2020). "Hypoalbuminemia is a rather nonspecific parameter to access hepatic function especially during sepsis, as increased vascular permeability and shifting to acute phase proteins production also contribute to the albumin decrease." (PMID 32539830, 2020). "First, it was not possible to have data on the patients’ albumin levels before study enrollment to determine whether the observed hypoalbuminemia was pre-existing or not." (PMID 31095609, 2019). "We hypothesized that sucroferric oxyhydroxide (SO), a potent phosphate binder with a low pill burden, may reduce serum phosphorus levels in hemodialysis patients with hypoalbuminemia without adversely impacting albumin levels or dietary intake of protein." (PMID 31664928, 2019). "Only a small fraction of our participants (3%) had hypoalbuminemia (serum albumin <3.5 g/dL), similar to the START study (2%) and the D:A:D trial (6%), suggesting that these patients are relatively healthy overall and would unlikely benefit from nutritional support to increase serum albumin." (PMID 30515432, 2018). "The serum albumin levels of 25 out of 39 c-maf-positive MM patients were lower than the normal level (35 g/L, 64.1%), while only 42.7% (n = 38 out of 89) c-maf-negative patients had hypoalbuminemia." (PMID 28560070, 2017). "Other inappropriate prescriptions were as follows: hypoalbuminemia in excess of albumin level of 2gr/dl, sepsis without septic shock, cirrhosis without hypoalbuminemia, edema responsive to diuretics, cerebral ischemia, chronic kidney disease, hypovolumia, and others." (PMID 28979337, 2017). "Note that serum albumin levels were not evaluated in the first two Cohorts and thus it was possible that the occurrence of hypoalbuminaemia may be underreported if these data for these patients were available." (PMID 28150073, 2017). "The mild hypoalbuminemia may also be explained by an inflammatory response as albumin is a negative acute phase protein which may decrease during inflammation." (PMID 27160919, 2016). "Also, 81% of individuals with congenital analbuminemia (dysfunction of the albumin gene resulting in marked hypoalbuminemia) have little or no edema." (PMID 26793696, 2015). "Whether hypoalbuminemia is a consequence of liver injury caused by HCC or liver dysfunction due to aging is not clear; however, low serum albumin level has been shown to affect the metabolism of drugs and to be associated with postoperative delirium." (PMID 25768121, 2015). "It is therefore reasonable to investigate whether the correction of hypoalbuminemia by infusion of human albumin could not lead to a reduction of AKI in such patients." (PMID 26136776, 2015). "Hypoalbuminemia was earlier detected in 81% (25 out of 31, data not shown) of these bitches with pyometra which is in line with other reports and also indicate that albumin could be interesting to study as a possible sepsis marker." (PMID 25430894, 2014). "Although the AG was higher among the AKI survivors, their albumin corrected AG was not significantly different from that of the nonsurvivors, which may have been the result of significant hypoalbuminemia among the nonsurvivors." (PMID 25162029, 2014).
Hypoalbuminemia (continued). "Since comorbid medical conditions may decrease albumin synthesis in the liver, hypoalbuminemia is a non-specific marker of denutrition and a difficult-to-modify patient factor, better associated with patient comorbidities than with poor quality of care." (PMID 23705852, 2013). "However, infusion of albumin in patients with hypoalbuminemia did not have an effect on the level of CRP." (PMID 24049653, 2012). "Other significantly different biological parameters between IgAN and non-IgAN, such as TP, ALB, CH, TG, LDL and sIgG, were also linked to the different proportion of nephrotic syndrome, which is characterized by mass proteinuria, hypoalbuminemia, edema, and varying degrees of hyperlipidemia." (PMID 22738421, 2012). "Increased vessel permeability also could not be responsible for the formation of hypoalbuminemia, because extravascular albumin pool of RA patients was decreased rather than increased." (PMID 23006786, 2012). "Albumin-adjusted calcium values are useful to consider for subjects with hypoalbuminemia, since non-adjusted total calcium can be reduced by a lower albumin-bound fraction, while the ionized physiologically active portion may be normal." (PMID 21884590, 2011). "Thus there is slight or no hypoalbuminemia in early stages of cancer but as the disease progresses albumin levels drop significantly and serve as good indicators of prognosis of cancer." (PMID 21176210, 2010). "Serum albumin level was measured in all patients and none of them had hypoalbuminemia." (PMID 21139715, 2010). "In addition, albumin infusion may increase the in-hospital mortality, as well as the length of stay in the ICU and the hospital among ICU patients with congestive heart failure -hypoalbuminemia overlap." (PMID 40773463, 2025). "However, hypoalbuminemia may not solely reflect decreased hepatic synthesis; it can also result from ALB leakage into the hepatic lymph or an expanded distribution volume, particularly in ascitic patients." (PMID 40453929, 2025). "That is, under albumin supplementation, patients with higher albumin levels tended to exhibit higher risks of mortality, shock, heart failure, and pulmonary edema, whereas albumin supplementation did not exert any significant influence on patients with severe hypoalbuminemia (0.0–1.0 g/dL)." (PMID 40649163, 2025). "However, routine administration of albumin may not always be advantageous for treating hypoalbuminemia." (PMID 40649163, 2025). "Our study found that compared to the normal ALB group, patients with hypoalbuminemia had a worse prognosis, but this was not an independent predictor of prognosis, which may be because ALB levels were also affected by ascites, body weight, and other nutrition-related indicators." (PMID 39886546, 2025). "Notably, this study did not consider albumin-corrected AG, which may be affected by hypoalbuminemia common in critically ill patients." (PMID 40486199, 2025). "Therefore, CPP is an effective source of albumin, and thus, although hypoalbuminemia might be treated with canine plasma (fresh or not), CPP should be considered in such cases, in clinical settings where CRYO is routinely produced from FFP." (PMID 40521764, 2025). "It hasbeen reported that hypoalbuminemia is the result of the combined effects ofinflammation and inadequate protein in patients with critical diseases.For these reasons, albumin, a negative acute-phase reactant, may be considered asurrogate marker of serious infectious disease." (PMID 39618856, 2024). "However, in severe cases of edema due to liver disease and hypoalbuminemia, traditional diuretics may not be as effective as they are unable to restore serum albumin levels." (PMID 39099956, 2024). "Therefore, mild or no hypoalbuminemia in the early stages of cancer, but a significant decrease in albumin levels as the disease progresses could be a good indicator of cancer prognosis." (PMID 39744624, 2024).
Hypoalbuminemia (continued). "Furthermore, albumin is known as a negative acute phase protein and hypoalbuminemia could therefore also be fostered by a systemic inflammatory state and a concomitant acute phase reaction resulting in extravasation and decreased hepatic albumin synthesis." (PMID 39834917, 2024). "The result of hypoalbuminemia in patients with cancer might be due to cancer patient, pro-inflammatory cytokines (TNF-α, IL-2, and IL-6) induced positive acute phase reactant synthesis compete for nutrient in liver leads to decreases in serum albumin production." (PMID 36869395, 2023). "Dogs with hypoalbuminemia have previously been shown to have more severe disease and a worse prognosis among dogs with CE, which was corroborated in our study by the finding of a moderately negative correlation of serum albumin concentration with the CCECAI index." (PMID 37505823, 2023). "Serum albumin concentration (sAlb; RI, 3.0–4.4 g/dL) was lower (p = 0.032) among the non-survivors (median, 3.19 g/dL; range, 1.3–4.9) than among the survivors (median, 3.5 g/dL; range, 1.1–5.3); and hypoalbuminemia (sAlb < 3 g/dL) occurred more frequently among the non-survivors (p = 0.003)." (PMID 37888640, 2023). "However, as albumin is also a negative inflammation marker, hypoalbuminaemia in old dogs may suggest subclinical conditions, similar to increased GlycA." (PMID 35223061, 2022). "Thus, hypoalbuminemia is not a consequence of reduced albumin production by the liver." (PMID 36232721, 2022). "However, patients with HAD and hypoalbuminemia had longer hospital LOS (median 5 vs. 4 days), higher percentage of prolonged LOS (34% vs. 20.4%), and a significantly higher 1yr mortality (55.2% vs. 27.7%, p < 0.001), compared with HAD patients with normal serum albumin." (PMID 35268297, 2022). "However, there is no consensus as to whether simply administering albumin to patients with hypoalbuminemia reduces their morbidity and mortality." (PMID 36077496, 2022). "The mechanism of hypoalbuminemia leads to delirium is unclear, it may be the albumin can not only transport a variety of trace elements and drugs but also has the functions of antioxidation, scavenging free radicals, and protecting the microcirculation, playing a vital role in the body’s metabolism." (PMID 35783136, 2022). "It is recommended that factors such as ALB and WT values should be considered in clinical practice, and monitoring of the caspofungin plasma concentration may be required for ICU patients with hypoalbuminaemia and for patients with significant changes in ALB levels and WT." (PMID 36408257, 2022). "In addition, as albumin has the ability to reduce tissue-damaging oxidative stress and acts as an anticoagulant due to its ability to bind AT III and inhibit platelet aggregation, hypoalbuminemia may further worsen the prognosis." (PMID 36016322, 2022). "However, study results on the combination of furosemide in conjunction with albumin, and on the efficacy of furosemide in hypoalbuminemia, did not confirm this hypothesis." (PMID 36556982, 2022). "Moreover, the limited sample size of the hypoalbuminemia group could lead to bias in the nonlinear relationship between serum albumin and hypertension." (PMID 34050200, 2021). "Albumin is a negative acute phase protein that decreases in acute inflammatory conditions; therefore, the induction of inflammatory conditions by the trypanosomes could lead to hypoalbuminemia." (PMID 34275459, 2021). "Hypoalbuminemia, which is a marker of cardiovascular disease in patients with CKD, and which was also observed in our DM + HFD + CKD swine, may result in a reduction of circulating albumin-bound NO, thereby shortening the half-life of produced NO and impairing NO-mediated vasodilation." (PMID 34435256, 2021).
Hypoalbuminemia (continued). "In addition, due to the link between albumin levels and ICU admissions as well as ARDS development, patients with severe hypoalbuminemia may benefit from admission to a higher level of care (e.g., intermediate care) compared to the general medical floor if available." (PMID 33725003, 2021). "He concluded that patients with hypoalbuminemia > 2.0 g/dL are unlikely to benefit from albumin infusion with furosemide treatment, while patients with serum albumin levels < 2.0 g/dL could potentially benefit from the co-administration of furosemide with albumin." (PMID 34851962, 2021). "Consequently, there is simply slight or even no hypoalbuminemia in early stages of cancer, but as the disease progresses the albumin levels drop significantly and may serve as ideal indicators of prognosis of cancer." (PMID 32982584, 2020). "Finally, lower baseline PA levels for most hypoalbuminaemic patients compared to those measured within 8–30-day period before the bacteraemia also indicated that hypoalbuminaemia primarily reflected acute, rather than chronic, conditions, especially given albumin’s long half-life of 20 days." (PMID 27611431, 2016). "Moreover, the number of patients receiving albumin infusion and the volume of albumin solutions were not recorded in this study, which might affect the prognostic analysis of patients with hypoalbuminemia." (PMID 26557421, 2015). "In addition, albumin is a negative acute phase protein and extensive inflammation may compound this hypoalbuminemia." (PMID 23578174, 2013). "However, unlike previous studies, our research also presents a new perspective with significant clinical implications: even when serum albumin levels have not yet reached the clinical diagnosis of “hypoalbuminemia,” lower values may still have adverse effects on tissue function." (PMID 40520340, 2025). "Third, albumin correction was not performed for SAG due to the lack of albumin records, despite of the impact of hypoalbuminemia on SAG concentrations as reported in some studies." (PMID 38418846, 2024). "Dogs with hypoalbuminemia displayed significantly more elevated CIC levels (p = 0.02), and low negative correlation was found between CIC and albumin levels (r = −0.306)." (PMID 38562919, 2024). "However, in such a range of plausible mechanisms leading to hypoalbuminemia in CKD patients (i.e., proteinuria, chronic inflammation, inappropriate nutrition), further studies are needed to detect in which type of patients the ALB supplementation may be more beneficial." (PMID 37762957, 2023). "According to the first, hypoalbuminemia should lead to lower concentrations of OTA in hepatocytes, because of the lack of albumin, which functions as a delivery system (‘lack of delivery concept’)." (PMID 35962801, 2022). "Four studies evaluating the relationship between hypoalbuminemia and CIPN were identified with three demonstrating a significant relationship and one that did not demonstrate a relationship between CIPN and albumin." (PMID 35054049, 2022). "The logistic regression model to predict 1 yr mortality in these non-HAD patients, including age, gender, CCI and albumin confirmed the strong effect of CCI (OR 1.26) and hypoalbuminemia (OR 4.49, p < 0.01), with AUC 0.79." (PMID 35268297, 2022). "In our study, albumin level of newborns in the RDS group is significantly lower than that in the control group, and the proportion of hypoalbuminemia is higher in the RDS group (but the difference was not statistically significant)." (PMID 34485188, 2021). "Indeed, the chronic low-grade inflammatory state of obesity might have reduced the levels of acute phase proteins, such as albumin; therefore, the observed hypoalbuminemia should be carefully interpreted, since it may not necessarily indicate a deficiency state." (PMID 33026590, 2021). "Although serum albumin levels significantly decreased in BI and BII group after surgery, no patient experienced hypoalbuminemia or protein malnutrition in all 3 groups." (PMID 34789863, 2021).